IDO2 (indoleamine 2,3-dioxygenase 2)
Diseases named in the same sentence as IDO2 in open-access papers (continued):
Sharing a sentence is not in itself a finding about the gene and the disease.
tumor (continued). "The observed co-expression of IDO2 and AhR, and the absence of associations between AhR and IDO1 or TDO2, may indicate a shift toward IDO2–AhR–driven immune suppression in advanced tumours." (PMID 40471422, 2025). "Moreover, IDO2 supports cancer cell migration and proliferation, but its inhibition can reduce tumor volume and increase the number of tumor-infiltrating immune cells." (PMID 40332338, 2025). "IDO2 expression and its functional role vary depending on the type of tumor." (PMID 41035912, 2025). "Importantly, IDO2 expression closely mirrored that of AhR and tumour cell density, reinforcing a potential regulatory link between the two." (PMID 40471422, 2025). "Nonetheless, IDO2 expression was closely aligned with AhR expression and tumour cellularity, while no such association was found between AhR and either IDO1 or TDO2." (PMID 40471422, 2025). "The deletion of Ido2 reduced the tumor volume in a mouse model of Lewis lung carcinoma." (PMID 39594642, 2024). "Additionally, IDO2 is mainly detected in certain tumor cells and is constitutively present in the liver, placenta, and central nervous system." (PMID 39492834, 2024). "Research studies suggest that blocking IDO2 could improve immune response by reducing tumor-induced immune suppression, however, clinical trials focused on IDO2 are still in the early stages, and their efficacy remains under investigation." (PMID 39594642, 2024). "The expression of IDO2 in trophoblasts could suggest a potential pro-tumorigenic role like that observed in tumor environments, and maybe support the “trophoblast model of cancer” hypothesis." (PMID 39594642, 2024). "Although the biological role of IDO2 in mice is still very uncertain and debated, some clues regarding the hIDO2 function in cancer could come from the literature on mIDO2 in tumor models." (PMID 39594642, 2024). "Indeed, it was demonstrated that IDO2 affects the proliferation, migration, and survival of murine tumor cells." (PMID 39594642, 2024). "Interestingly, the reduced tumor growth of lung carcinoma cells was found in IDO2-knockout mice compared with wildtype mice." (PMID 37408267, 2023). "However, the relevance of IDO2 in the suppression of the anticancer immune response and tumor promotion is still unclear." (PMID 37408267, 2023). "This indicates that IDO2 may play a role on tumor immune resistance and may thus be regarded as a potential target for cancer immunotherapy." (PMID 36319978, 2022). "IDO2 depletion altered the tumor microenvironment, leading to the enhancement of immune cell invasion, which suggests that IDO2 is an important immune regulator in the tumor microenvironment." (PMID 36319978, 2022). "The pT stage of MTC is associated with the maximum tumor size and extrathyroidal extension, but the results showed that IDO2 expression was not correlated with maximum tumor size." (PMID 36319978, 2022). "CB1R and IDO2 also stimulate angiogenesis and the ingrowth of new vessels to the developing tumour." (PMID 35354487, 2022). "A number of studies have focused on the effects of IDO2 on tumor immune resistance." (PMID 36319978, 2022). "A number of studies have reported the effects of IDO2 on tumor immune resistance." (PMID 36319978, 2022). "Thus, as a whole, the available data would indicate that IDO2, either endogenous or expressed by the tumor, exerts immunosuppressive and pro-tumor effects in mouse models of cancer." (PMID 33968089, 2021). "However, the opportunity to use Ido2−/− mice as compared to IDO2-expressing counterparts allows the study of the function of endogenous IDO2 in tumor-bearing individuals." (PMID 33968089, 2021). "In this regard, the lack of a statistically significant correlation between DFS and the high tumor expression of both IDO2 and IDO1 could appear to be a confounding result, in particular when compared to the OS analysis of the current series." (PMID 32536910, 2020).
tumor (continued). "In addition, regarding patients with a high tumor expression of IDO2, the probability of death within 36 months was roughly 18% compared to almost 7% for the group with a low expression of IDO2 (p < 0.001)." (PMID 32536910, 2020). "Furthermore, we found that IDO2 expression in IDO2 shRNA tumor tissue still maintained 80% gene silencing 22 days after cell inoculation." (PMID 27058624, 2016). "In addition to tumor onset time, we found that tumor growth was constrained in IDO2 shRNA stable cells injected mice compared with scrambled shRNA stable cells injected mice." (PMID 27058624, 2016). "The data indicate that silencing IDO2 can significantly inhibit tumor cell migration." (PMID 27058624, 2016). "Tumor weight derived from IDO2 shRNA treated mice was less than scrambled shRNA treated mice." (PMID 27058624, 2016). "In addition to in vitro findings, we also demonstrate that IDO2 silencing in tumor cells using short hairpin RNA (shRNA) delayed tumor formation and arrested tumor growth in vivo." (PMID 27058624, 2016). "To explore the therapeutic effect of silencing IDO2, we treated tumor-bearing mice with IDO2 shRNA." (PMID 27058624, 2016). "In addition to these in vitro findings, we also showed that using shRNA to silence IDO2 in tumor cells delayed tumor formation and arrested tumor growth in vivo, providing a potentially new therapy for cancer." (PMID 27058624, 2016). "Systemic treatment with IDO2 shRNA may not only impair tumor function but it may also change the host immune system, leading to an overall reduction of tumor burden." (PMID 27058624, 2016). "The IDO2 protein was detected by Western blot in three IFNγ-incubated tumor cell lines." (PMID 25691885, 2015). "The significant increase in both IDO-1 and IDO-2 expression in response to IFN-γ stimulation may suggest that both enzymes could contribute to tumor progression by inhibiting specific tumor immunity." (PMID 25415278, 2014). "In this respect, IDO2 expression has been found in human tumors, including gastric, colon, renal, and in pancreatic tumors IDO2 expression have been found both in tumor cells as well as in immune cells in tumor-draining LN." (PMID 22388712, 2012). "Whether IDO2 functions similarly in a tumor context requires further investigation." (PMID 40103267, 2025). "Notably, IDO2 exhibited a strong association with AhR expression and tumour cell density, with no observed correlation between AhR and either IDO1 or TDO2." (PMID 40471422, 2025). "However, we found a strong correlation between IDO2-AhR which may be responsible for the sustained and enhanced immunosuppression within the tumour microenvironment." (PMID 40471422, 2025). "That the IDO2 may be involved in immune evasion by tumor has also been suggested in tumor biology." (PMID 38674162, 2024). "IDO2 may promote tumor immune suppression through the Trp-Kyn-AhR axis." (PMID 37876966, 2023). "Surprisingly, although Ido1, Ido2 and Tdo2 were barely expressed in MEPs, a high level of Kyn was found in the MEPs of tumor-bearing mice and a very low Kyn level was present in the MEPs of tumor-free mice, suggesting that MEPs from tumor-bearing hosts might use exogenous Kyn to activate AhR." (PMID 37919525, 2023). "Moreover, IDO2 absence in this setting altered the tumor microenvironment and increased the accumulation of tryptophan, resulting in an enhanced immune cell infiltration, which indicates that IDO2 may play a critical role in shaping the tumor microenvironment." (PMID 37408267, 2023). "Therefore, both IDO1 and IDO2 may play an important role in cancer by inducing tumor-immune tolerance through enzyme-dependent and enzyme-independent IDO-mediated immunosuppression." (PMID 37408267, 2023). "Therefore, the definition of the IDO2 interactome and function in distinct neoplasia may open innovative avenues of therapeutic interventions." (PMID 33968089, 2021).
tumor (continued). "However, the relationship between the IDO2 associated immune response and tumor progression has not been elucidated." (PMID 33619235, 2021). "Furthermore, IDO2-/- mice display a decreased tumor size compared with wild-type mice." (PMID 34422661, 2021). "Consequently, the increased IDO2 expression in NSCLC could likely occur when the tumor cells are closely in contact with the inflammatory infiltrate, and could be interpreted as a tumor attempt to evade the immune system attack." (PMID 32536910, 2020). "Moreover, from the long follow-up period we highlighted an increasing difference in the probability of death between the patients belonging to the group with a high tumor expression of IDO2 and those belonging to the low expression group (28% compared to near 12% within 60 months)." (PMID 32536910, 2020). "Our aim was to explore the correlation between key KP markers; IDO1, IDO2, TDO2, its primary effector target aryl hydrocarbon receptor (AhR) and a comprehensive set of clinical- and tumour characteristics." (PMID 40471422, 2025). "Our aim is to investigate the KP with a broadened scope, exploring the IDO1, IDO2, TDO2 and AhR interplay with both clinical as well as tumour characteristics." (PMID 40471422, 2025). "TDO, IDO1, and IDO2, which catalyze the first and rate-limiting step of TRP degradation via the KP, leading to NFK generation, are involved in tumor development and immune modulation." (PMID 40332338, 2025). "Immunohistochemical analysis on glioblastoma TMA cores showed variable cytoplasmic expression of IDO1, IDO2, and TDO2, while AhR showed variable nuclear expression in tumour cells across GBM patients." (PMID 38951170, 2024). "IDO1 is positively correlated with CD274, TNFRSF9, TNFRSF4, PDCD1LG2, IDO2, and CD48 in many tumor types." (PMID 38539263, 2024). "The expression of IDO2 curtails the proliferation of CD4+ and CD8+T cells, and impedes the infiltration of CD4+ T cells into tumor sites." (PMID 39492834, 2024). "We evaluated the IHC staining of Trp‐catabolizing enzymes, including IDO1, IDO2, TDO2, and IL4I1, in tumor cells." (PMID 37148546, 2023). "The degradation of Tryptophan to Kynurenine is catabolized by tryptophan enzymes, including IDO1, IDO2, TDO2, and IL4I1, which up‐regulate PD‐L1 expression and promote tumor suppressive microenvironment in various cancers." (PMID 37148546, 2023). "IDO1, IDO2, and TDO2 contribute to the noteworthy local catabolism of Trp, and these enzymes, along with PD‐L1, play a crucial role in tumor immune escape." (PMID 37148546, 2023). "Immune Checkpoints are expressed by different cell types such as T cells (PD1, TIGIT), macrophages, dendritic cells, and tumor cells (PDL1 and IDO2)." (PMID 38260202, 2023). "In the tumor samples, F2, GLS2, IDO2, and PLAUR were shown to be significantly upregulated, while GNG7, PIK3CG, and ST3GAL6 were significantly down-regulated." (PMID 33619235, 2021). "In the tumor tissue, expression of IDO1 was greater than its isoform IDO2, suggesting a regulatory role for IDO1 in mediating immunosuppression and inducing downstream GCN2 expression." (PMID 27705910, 2016). "Using siRNA to knockdown IDO2 expression in B16-BL6 cells, we have shown that the role of IDO2 in tumor development and progression is correlated with the production of NAD+ and ROS." (PMID 27058624, 2016). "Of the 80 specimens examined, the ‘high IDO expression’ (IDO2+ or 3+) were found in 37 (46%) cases, of which 25 (31%) were IDO2+ and 12 (15%) were IDO3+, IDO−, and IDO1+ tumours were found in 15 (19%) and 28 (35%) cases, respectively." (PMID 17117179, 2006). "Kynurenine is a stable intermediate of the kynurenine pathway, and increased levels (along with increased IDO1 and IDO2) are often detected within the tumor microenvironment, suggesting their negative impact on tumor growth." (PMID 40766249, 2025).
tumor (continued). "Despite limitations, including analysis of adjacent (non-identical) tumour sections and a restricted immune panel, we found that IDO2 expression was enriched in tumour-dense regions with reduced macrophage and T cell presence." (PMID 40471422, 2025). "Emerging evidence suggests that the nonenzymatic roles of IDO2 also influence tumor progression, as it minimally contributes to Trp metabolism in cancer cells." (PMID 41332472, 2025). "As TDO2 has also been shown to promote tumor growth in some cancers, it is reasonable to speculate that TDO2 and IDO2 may act as compensatory pathways to continue KYN production and influence tumor immunity when IDO1 is inhibited." (PMID 40103267, 2025). "Despite the extensive literature describing the presence of IDO2 in tumor cells, so far there is no certain information about its function in cancer onset/progression in humans." (PMID 39594642, 2024). "Similarly, Ido2 gene silencing slowed B16-BL6 cell proliferation, significantly inhibited tumor cell migration and tumor growth, and affected cell cycle phases both increasing and decreasing cell accumulation in G1 and G2/M, respectively." (PMID 39594642, 2024). "In addition, kynurenine acts via AHR to degrade the adhesion molecule E-cadherin, resulting in enhanced tumor invasion, which is reduced by 1-MT, probably consistent with a role for IDO1 or IDO2." (PMID 37296860, 2023). "At harvest, tumor tissues were collected and assayed for IDO1/TDO2 and IDO2 protein expression." (PMID 37226257, 2023). "As TDO appears to be up-regulated in more cancer types than has hitherto been assumed and appears to be a prognostic factor in patient survival, tumour tissues should be assessed for TDO2 in addition to IDO1 and IDO2 before embarking on mono or multiple therapies with inhibitors of these enzymes." (PMID 36286592, 2022). "Unlike IDO1, the real IDO2 cellular function is poorly understood even today, in both normal and tumor cells." (PMID 32536910, 2020). "Initially, we measured IDO2 expression in a panel of mouse tumor cell lines of differing histological origin (data not shown)." (PMID 27058624, 2016). "In this study, we investigate the biological function of IDO2 in melanoma cancer cells using RNAi to elucidate the non-immune function of IDO2 and its mechanism in tumor growth." (PMID 27058624, 2016). "This difference might be attributed to the reduction of NAD+, which resulted from silencing IDO2, as NAD+ is required and highly consumed by tumor cells." (PMID 27058624, 2016). "We also confirmed the absence of detectable IDO2 expression by RT-qPCR in 128 human tumor samples and 25 human tumor cell lines of various histological types using primers amplifying exons 4–9 (data not shown)." (PMID 25691885, 2015). "Since only one case revealed negative IDO2 protein expression in tumor cells, the survival analysis on IDO2 protein expression in NK/TCL could not be performed." (PMID 37148546, 2023). "The analysis of the immune landscape in the OM group indicates a shift from a possible “hot” tumor suppressed by immune checkpoints (PDL1) to significantly heightened expression not only of those checkpoints but also the inclusion of other immune blockades such as PD1 and IDO2." (PMID 38260202, 2023). "Moreover, a close relationship between IDO2 expression, increased PD-L1 levels, tumor-infiltrating lymphocytes localization, and NSCLC poor prognosis was detected, making it possible for IDO2 to be a potential prognostic biomarker or part of combined therapies with immune checkpoint inhibitors." (PMID 36319978, 2022). "Using mRNA from diffuse and intestinal GC tumor samples of a Western cohort, this study reports the expression level of the immunomodulatory aryl-hydrocarbon receptor (AhR), and genes involved in immune suppression (PD1, PD-L1, PD-L2) and the early steps of tryptophan metabolism (IDO1, IDO2, TDO2)." (PMID 35203450, 2022).
tumor (continued). "Furthermore, DC_c1 cells might have functional alteration and enhanced lipid utilization due to the remodeling of TME as the increased expression of CXCL9, IDO2, APOA2, and APOE compared to their non-tumor counterparts." (PMID 33298893, 2020). "However, the role of IDO2 in affecting the anti-cancer immune response is less clear with the analysis of 129 human tumor samples and 25 human tumor cell lines showing no detectable full-length IDO2 mRNA transcript." (PMID 32612606, 2020). "Tryptanthrin and its analogs were shown to be anti-tumor agents both in vitro on cancer cell lines and in vivo on rat model, being potent inhibitors of indoleamine 2,3-dioxygenase (IDO1), tryptophan 2,3-dioxygenase (TDO) and indoleamine 2,3-dioxygenase 2 (IDO2)." (PMID 33374765, 2020). "Moreover, tumour-bearing DCs co-cultured with cryo-thermal eosinophils resulted in a significant down-regulation of immunosuppressive molecules, HO-1, STAT3, Foxo3, IDO2, VEGFR2 and PD-L1 as compared to tumour-bearing DCs co-cultured with tumour-bearing eosinophils." (PMID 31519961, 2019). "There are almost no reports of IDO2 function in tumor cells or tumor formation and growth." (PMID 27058624, 2016). "Although this suggests that IDO2 may also possess non-immune function on tumor biological characters, the physiological and pathological roles of IDO2 remain unclear." (PMID 27058624, 2016). "One of the strongest mediators of the tumor-induced immunosuppression is kynurenine, the product of tryptophan catabolism via tryptophan dioxygenase (TDO) and indoleamine 2,3-dioxygenase enzymes (IDO1 and IDO2), which are induced by interferon- γ (IFN-γ), nitric oxide (NO) and iron." (PMID 25955018, 2015). "Moreover, almost all tumors expressing PD-L1 coexpress IDO (not specified if IDO1 or IDO2 as well), but more than half of tumor-expressing IDO lacks PD-L1 expression, suggesting that IDO-expressing tumors are significantly more common than PD-L1–expressing ones." (PMID 36119020, 2022). "Moreover, the potential to knockdown IDO2 using RNAi to prevent tumor growth has not been explored." (PMID 27058624, 2016). "In addition, selective IDO1 blockade may not be sufficient to alleviate tumor immunosuppression, and IDO2/TDO may serve as an enzyme with a potential compensatory mechanism to attenuate the efficacy of epacadostat, a possible reason for its failure of phase III clinical trial." (PMID 39585774, 2025). "To determine the impact of IDO on tumor growth, we confirmed that IDO1, not IDO2, was induced following tumor establishment in the lungs of both WT and IDO-deficient mice." (PMID 27705910, 2016).